LINC02694 (long independently transcribed non-coding RNA 2694)
Synonyms: C15orf53; FLJ35695; LOC105370775; LOC124900600
Gene: Long non-coding RNA gene on chromosome 15 (38,577,150 to 39,180,499, forward strand). Ensembl gene ENSG00000175779.
Diseases named in the same sentence as LINC02694 in open-access papers:
LINC02694 is named in the same sentence as 6 diseases in open-access papers, as found by Europe PMC text mining. Sharing a sentence is not in itself a finding about the gene and the disease.
LINC02694 shares sentences with these, for which no sentence is quoted: alcohol dependence (2 papers); autism spectrum disorder (1); bipolar disorder (1); hereditary spastic paraparesis (1); Intellectual disability (1); Spastic paraplegia (1).